KLK10 (kallikrein related peptidase 10)
Diseases named in the same sentence as KLK10 in open-access papers (continued):
Sharing a sentence is not in itself a finding about the gene and the disease.
ovarian carcinoma (continued). "Consistent with this argument, a recent study showed that catalytically inactive KLK10, another member of this gene family, displayed a role as a tumor suppressor on ES2 ovarian cancer cells both in vitro and in vivo." (PMID 23451143, 2013). "KLK10 (kallikrein-10) is reportedly targeted by many microRNAs, such as let-7f, miR-224, and miR-516a, whose overexpression in ovarian cancer can lead to negative effects on cell proliferation." (PMID 30589909, 2018). "Six kallikreins, KLK4, KLK5, KLK6, KLK7, KLK10, and KLK15, are markers of poor prognosis in ovarian cancer." (PMID 20354523, 2010). "In addition to the negative impact of KLK10 and KLK11 expression in TNBC on patient prognosis, the contradictory data from other cancer entities, such as ovarian cancer, cannot yet be explained." (PMID 36294951, 2022).
prostate carcinoma (13 papers, 2002 to 2024). A carcinoma that arises from epithelial cells of the prostate gland. "Our functional studies confirmed the important role of the KLK10 gene in the tumour suppression of the KLK10-deficient, androgen-independent prostate cancer cell line PC3." (PMID 26616394, 2015). "KLK10 promoter methylation has been implicated in head and neck squamous cell carcinoma progression, as well as a potential prostate cancer and non-small cell lung cancer biomarker." (PMID 25472429, 2014). "The expression of KLK10 was down-regulated during breast cancer progression and prostate cancer tissue." (PMID 38707515, 2024). "Previously it has been reported that KLK10 promotes apoptosis of PC3 cells (one of the prostate cancer cells z via the down-regulation of Bcl-2)." (PMID 38707515, 2024). "Kallikrein‐related peptidase 10 (KLK10) is homologue to KLK3 and encodes the prostate‐specific antigen, which is a widely used biomarker for the detection and monitoring of prostate cancer." (PMID 29377588, 2018). "Our study confirms that the expression of KLK10 in prostate cancer tissue and cell lines (PC3, DU145, and LNCaP clone FGC) is low." (PMID 26616394, 2015). "Given that the androgen-independent growth characteristic of the PC3 cell line is more similar to clinical castration-resistant prostate cancer, we studied the role of KLK10 in PC3." (PMID 26616394, 2015). "Considering the androgen-independent growth characteristics of the PC3 cell line, it was chosen in our study as an advanced prostate cancer model to investigate the effect of KLK10 on cancer proliferation, apoptosis and glucose metabolism." (PMID 26616394, 2015). "In our study, we utilised 18F-FDG micro PET/CT scan to mimic the clinical situation for monitoring the effect of KLK10 gene therapy on prostate cancer in vivo." (PMID 26616394, 2015). "The present results confirmed that KLK10 expression was down-regulated in prostate cancer tissue and cell lines, including PC3, LNCaP clone FGC and DU145." (PMID 26616394, 2015). "In the current study, we confirmed that the expression of KLK10 was low in prostate cancer tissue and cell lines, including LNCaP clone FGC and PC3." (PMID 26616394, 2015). "Current studies have shown that the differential expression of KLK10 could regulate apoptosis in colorectal cancer cells, human prostate cancer cells, and esophageal cancer cells." (PMID 38707515, 2024). "In contrast, KLK10 was also proposed to have a tumor-suppressor role in breast and prostate cancer." (PMID 37550405, 2023). "It was examined that hypermethylation of KLK10 CpG island functions a crucially significant role in tumor-specific loss and downregulation of KLK10 mRNA and protein expressions in ALL, breast, and prostate cancers." (PMID 35669967, 2022). "Further experiments are needed to explore the underlying mechanism and the role of KLK10 in the KLK10-deficient, androgen-dependent prostate cancer cell line LNCaP clone FGC to understand the mechanism of KLK10 in prostate cancer and explore new potential targets for therapy." (PMID 26616394, 2015). "However, few studies have focused on the function of KLK10 in human prostate cancer." (PMID 26616394, 2015). "KLK10 represents a potential tumor suppressor, and its mRNA and protein expressions are downregulated in ALL and breast and prostate cancers." (PMID 35669967, 2022). "In the prostate cancer cell lines (PC3, DU145 and LNCaP clone FGC), KLK10 mRNA and protein expression was significantly lower than that in the normal prostate epithelial cell line (RWPE-1)." (PMID 26616394, 2015). "As an androgen-independent prostate cancer cell line, the PC3 cell line was investigated for KLK10 function in prostate cancer." (PMID 26616394, 2015).
prostate carcinoma (continued). "Liquid biopsy of exosomes isolated from patients with prostate cancer revealed that exosomes are enriched for genes that are hallmarks of prostate cancer, such as androgen receptor, kallikreins (KLK2), cyclin-dependent kinase inhibitor 1A (CDKN1A), KLK10, JUN, and B2M (β2 microglobulin)." (PMID 36726968, 2022).
colorectal cancer (8 papers, 2008 to 2024). A primary or metastatic malignant neoplasm that affects the colon or rectum. "It was reported that KLK10 overexpression has the potential to function as a diagnostic and prognostic biomarker for pancreatic and colorectal cancers." (PMID 35669967, 2022). "KLK10 has been reported up-regulated in gastric as well as colorectal carcinomas and associated with invasion and more advanced clinical stage for both types of tumors." (PMID 18302799, 2008). "In contrast, KLK10 is upregulated in thyroid, gastric, and colorectal cancers and promotes tumors." (PMID 31612115, 2019). "This miRNA is also downregulated in colorectal cancer (CRC) and targets KLK10 to inhibit its proliferation, verifying its tumor-suppressive roles." (PMID 38342922, 2024). "KLK10 provided the best example of subgroup-specificity, being hypermethylated in 48% of Lynch syndrome-colorectal cancers compared to 8% for sporadic MSI and 12% for sporadic MSS colorectal cancers." (PMID 27047543, 2016).
colon cancer (7 papers, 2009 to 2022). "The expression level of KLK10 is significantly higher in ovarian, pancreatic and colon cancer compared to normal tissues." (PMID 30267012, 2018). "We showed that, although many KLKs transcripts are upregulated in colon cancer-derived cell lines, KLK6, KLK10, and KLK11 are the most highly secreted proteins." (PMID 35883559, 2022). "Of these, six mRNA including ECM1, GZMB, KLK10, CCL20, MMP9, and IL7 have been previously reported to have a prognostic role in colon cancer." (PMID 29377588, 2018). "Colon cancer had four up-regulated KLKs with excellent AUC values (KLK6: 0.988, KLK7: 0.939, KLK8: 0.928, KLK10: 0.905)." (PMID 29707153, 2018). "Among the markedly increased genes in SSA/Ps that have also been reported to be increased in colon cancer were REG4, AQP5, MUC2, TFF1, KLK10." (PMID 24533081, 2014). "Nine KLKs (KLK5-8, KLK10, KLK11, KLK13-15) were measured using ELISA assays in cytosolic extracts of 122 colon cancer tissues and their nearby normal mucosa, obtained during surgery." (PMID 19367279, 2009).
gastric cancer (7 papers, 2015 to 2022). A primary or metastatic malignant neoplasm involving the stomach. "Overexpression of KLK10 mRNA was found to be an independent biomarker to predict a poor prognosis in gastric cancer, also urinary KLK10 protein played as a non-invasive biomarker to predict inoperable and incurable gastric cancer." (PMID 35669967, 2022). "KLK10 plays essential roles in tumor invasion and metastasis in gastric cancer and epithelial ovarian carcinomas." (PMID 28678795, 2017). "NES1/KLK10 pathway, COL4A1, microRNA-21/PTEN pathway, miR-223/FBXW7 pathway, etc. contributed to trastuzumab resistance of gastric cancer." (PMID 33623790, 2021). "The exon 3 CpG island methylation of Klk10 is found in breast, ovarian, prostate, acute lymphoblastic leukemia (ALL), and gastric cancers." (PMID 26151867, 2015).
pancreatic cancer (7 papers, 2008 to 2025). "Elevated KLK10 expression is associated with poor prognosis in pancreatic cancer." (PMID 41008826, 2025). "KLK10 also mediates pancreatic cancer invasion and metastasis by activating the FAK-SRC-ERK signaling pathway." (PMID 31612115, 2019). "KLK10 is upregulated in pancreatic cancer patients with lymph node involvement and remote metastasis." (PMID 31612115, 2019). "KLK10 knockdown attenuated pancreatic cancer cell migration, invasion, and metastasis in vitro and in vivo." (PMID 31612115, 2019). "In pancreatic cancer, KLK10 is highly expressed in pancreatic intraepithelial neoplasia and cancer tissues." (PMID 31612115, 2019). "To ascertain the contribution of KLK10 to pancreatic cancer microenvironment, we used siRNA-mediated gene-silencing." (PMID 18854834, 2008). "Furthermore, KLK10 enhances epithelial–mesenchymal transition (EMT) and activates FAK-SRC-ERK signaling, thereby promoting invasion and metastasis in pancreatic cancer, further implicating KLK10 in PDAC initiation and progression." (PMID 41008826, 2025). "KLK10 contributes to the pancreatic tumor microenvironment by modulating cellular motility." (PMID 41008826, 2025). "KLK6, KLK7, KLK8, KLK10 and KLK11 were coexpressed and upregulated in tissues from pancreatic cancer patients compared to normal pancreas." (PMID 34439122, 2021). "KLK10 and KLK6 are co-expressed in pancreatic cancer tissues, positively correlated with R1-resection status and poor prognosis and are independent risk factors." (PMID 31612115, 2019). "KLK10 and KLK6 are among the most highly and specifically overexpressed genes in pancreatic cancer compared with normal and benign pancreas tissues." (PMID 18854834, 2008). "Our findings confirm the KLK6-specific effects as APPI-4M reduced the KLK6 secretion of pancreatic cancer cells, while KLK10 secretion was not affected." (PMID 34439122, 2021). "Although high expression in pancreatic carcinoma indicates that KLK6 and 10 could be promising tumour markers, we could not assess the use of KLK6 and KLK10 as serum biomarkers in PDAC." (PMID 18854834, 2008).
pancreatic ductal adenocarcinoma (7 papers, 2008 to 2025). An infiltrating adenocarcinoma that arises from the epithelial cells of the pancreas. "For example, some studies have reported that KLK10 is elevated in pancreatic ductal adenocarcinoma tissues, and that aberrant KLK10 expression is associated with poor prognosis and shorter survival." (PMID 37550405, 2023). "Recent research has identified KLK6 as a promising prognostic biomarker in various cancers, while the co-expression of KLK6 and KLK10 has been suggested as a potential indicator of survival outcomes in pancreatic ductal adenocarcinoma." (PMID 40428321, 2025). "IFI27 showed high expression in ductal cells and fibroblasts, whereas KLK10 was strongly expressed in ductal cells, suggesting that IFI27 and KLK10 could be closely linked to the development of pancreatic ductal carcinoma." (PMID 41008826, 2025). "The existing literature has emphasized that the amplification of the EMT and FAK/SRC/ERK axes may contribute to the metastasis of pancreatic ductal adenocarcinoma by upregulating KLK-10 expression." (PMID 37686036, 2023). "Previous studies suggested an upregulation of KLK10 and KLK6 in pancreatic ductal adenocarcinoma (PDAC)." (PMID 18854834, 2008).
atherosclerosis (4 papers, 2013 to 2025). A disease characterized by the build-up of fatty material and calcium deposition in the arterial wall resulting in partial or complete occlusion of the arterial lumen. "Together, the anti-inflammatory and barrier-protective effects of KLK10 lead to an overall protection against atherosclerosis." (PMID 35014606, 2022). "The protective effects of rKLK10 or plasmid-driven KLK10 expression on endothelial inflammation, barrier function, and atherosclerosis suggest its therapeutic potential for atherosclerosis treatment." (PMID 35014606, 2022). "Flow-sensitive KLK10 inhibits endothelial inflammation and protects permeability barrier, ultimately reducing atherosclerosis." (PMID 35014606, 2022). "In a recent study, expression of Klk10 was down-regulated in mouse carotid artery after a partial ligation which rapidly induces atherosclerosis." (PMID 23977389, 2013). "Ultrasound-mediated overexpression of Klk10 plasmid inhibits atherosclerosis development." (PMID 35014606, 2022). "We next asked whether overexpression of KLK10 using a plasmid vector could also inhibit atherosclerosis in vivo." (PMID 35014606, 2022). "Previously, we identified kallikrein-related peptidase 10 (Klk10, a secreted serine protease) as a flow-sensitive gene in mouse arterial ECs, but its role in endothelial biology and atherosclerosis was unknown." (PMID 35014606, 2022). "Additionally, rKLK10 injection or ultrasound-mediated transfection of Klk10-expressing plasmids inhibited atherosclerosis in Apoe−/− mice." (PMID 35014606, 2022). "Moreover, treatment with rKLK10 or overexpression of KLK10 by ultrasound-mediated plasmid expression inhibited endothelial inflammation and atherosclerosis development in vivo." (PMID 35014606, 2022). "We next tested if KLK10 regulates EC function by evaluating its role in endothelial inflammatory response, tube formation, migration, proliferation, and apoptosis, which play critical roles in the pathogenesis of atherosclerosis." (PMID 35014606, 2022). "However, the role of KLK10 for endothelial function and atherosclerosis is not known." (PMID 35014606, 2022).
cervical cancer (4 papers, 2019 to 2024). A primary or metastatic malignant neoplasm involving the cervix. "Sp1 knockdown increased kallikrein-10 (KLK10) expression, indicating that the miR-7/Sp1 axis acts as a key regulator of MTA2, affecting both KLK10 expression and mobility in cervical cancer cells." (PMID 38632598, 2024). "Another miRNA 199b-5p was reported to promote metastasis in cervical cancer by downregulating kallikrein-related peptidase 10 (KLK10)." (PMID 33777808, 2021).
colon adenocarcinoma (4 papers, 2018 to 2025). "KLK6, KLK7, KLK8, and KLK10 were recently reported as potential diagnostic biomarkers for colon adenocarcinoma." (PMID 36293321, 2022). "Recent analysis of kallikrein gene family across 15 different cancers highlighted KLK6, KLK7, KLK8, and KLK10 as the excellent diagnostic biomarkers candidates for colon adenocarcinoma." (PMID 34065672, 2021). "KLK6, KLK7, KLK8 and KLK10 are considered as excellent biomarker candidates in diagnosing colon adenocarcinoma." (PMID 40156045, 2025).
lung carcinoma (3 papers, 2018 to 2022). "KLK10 expression is downregulated in breast, prostate, testicular, and lung cancer but overexpressed in ovarian, pancreatic, and uterine cancer." (PMID 35014606, 2022). "KLK10 was initially discovered as a potential tumor suppressor with its expression downregulated in breast, prostate, testicular, and lung cancer." (PMID 35014606, 2022). "Except KLK10, all other genes were already known to have a role in lung cancer." (PMID 36046142, 2021).
triple-negative breast carcinoma (3 papers, 2022 to 2023). An invasive breast carcinoma which is negative for expression of estrogen receptor (ER), progesterone receptor (PR), and human epidermal growth factor receptor 2 (HER2). "In the present study, we quantified mRNA expression levels of KLK10 and KLK11 in a well-defined cohort of patients afflicted with triple-negative breast cancer, and evaluated their potential as prognostic factors." (PMID 36294951, 2022).
frontotemporal dementia (2 papers, 2019 to 2023). Frontotemporal dementia (FTD) comprises a group of neurodegenerative disorders, characterized by progressive changes in behavior, executive dysfunction and language impairment, as a result of degeneration of the medial prefrontal and frontoinsular cortices. "For instance, lower levels of KLK10 have been found in the CSF of frontotemporal dementia and AD patients." (PMID 37667404, 2023).
head and neck squamous cell carcinoma (2 papers, 2014). A squamous cell carcinoma that arises from any of the following anatomic sites: lip and oral cavity, nasal cavity, paranasal sinuses, pharynx, larynx, and salivary glands. "Correlative studies have already provided evidence that five other protein members of KLK family (KLK4, KLK5, KLK7, KLK8, and KLK10) were abundantly expressed in head and neck squamous cell carcinoma, showing diagnostic value." (PMID 24669031, 2014).
liver cancer (2 papers, 2016 to 2024). An epithelial or non-epithelial malignant neoplasm that arises from the liver. "In summary, these data suggest the crucial role of miR-141 in liver cancer development via targeting KLK10 and TNFSF-15 and provide miR-141 as an attractive candidate in liver cancer treatment and protection." (PMID 38866875, 2024). "Interestingly, the experimental rats with liver cancer induced by Diethylnitrosamine injection further confirmed the upregulation of miR-141 level, IL-10, and TNF-α and the disturbance in KLK10 and TNFSF-15 gene expression compared with their expression in normal rats." (PMID 38866875, 2024).
melanoma (2 papers, 2011 to 2022). A malignant, usually aggressive tumor composed of atypical, neoplastic melanocytes. "In this work, we observed that the overall survival outcome was significantly associated with a high level of PDGFA and a low level of KLK6 and KLK10 expression in melanoma tumors and that these genes were expressed in an opposite way in XP patients who developed melanoma at a young age." (PMID 35974070, 2022). "Further exploration with larger sample size is required to confirm the current findings and to examine the consequences of the altered transcriptional profile especially concerning KLK6 and KLK10 who may contribute to the worsening of Melanoma tumorigenesis." (PMID 35974070, 2022).
serous ovarian cancer (2 papers, 2017 to 2019). "Consistent with these earlier studies, we showed that most of the advanced high-grade serous ovarian cancer samples displayed robust expression of KLK10 and KLK11." (PMID 29095848, 2017). "In summary, whereas KLK9 and KLK10 mRNA expression does not display any prognostic power in advanced high-grade serous ovarian cancer (FIGO stage III/IV), high KLK15 and, especially, KLK11 mRNA levels are associated with better outcome." (PMID 29095848, 2017). "Therefore, it is not too surprising that we observed indication for coordinate expression of some KLKs such as KLK6/KLK8 (Spearman correlation of mRNA levels: rs = 0.636;), KLK10/KLK11 (rs = 0.647;), or KLK5/KLK7 (rs = 0.568; unpublished results) in advanced high-grade serous ovarian cancer." (PMID 30811511, 2019).
astrocytoma (1 paper, 2015). "Like KLK6, higher levels of KLK1, KLK7, KLK8, KLK9 and KLK10 were all found to be associated with higher astrocytoma grade." (PMID 26231762, 2015). "In this study we determined KLK1, KLK6, KLK7, KLK8, KLK9 and KLK10 protein expression in two independent tissue microarrays containing 60 grade IV and 8 grade III astrocytoma samples." (PMID 26231762, 2015). "Expression of KLK1, KLK6, KLK7, KLK8, KLK9 and KLK10 protein was assessed by immunohistochemical analysis of grade III (n = 8) and grade IV (n = 60, n = 55 for KLK1) astrocytoma samples." (PMID 26231762, 2015).
benign ovarian tumors (1 paper, 2018). "Additionally, we assessed KLK10 exon 3 methylation in benign ovarian tumors (not included in the previous work) and found that they were unmethylated." (PMID 29690914, 2018). "Additionally, we studied KLK10 exon 3 methylation in benign ovarian tumors – not included in the previous work – and they all were unmethylated." (PMID 29690914, 2018).
carcinoma in-situ (1 paper, 2026). "We found that upregulation of KLK7 and KLK10 RNA and protein occurs early in tumor development and marks carcinoma in-situ lesions (stage 0, PanIN3) and early-stage (stage 1) PDAC, while non-cancerous low grade lesions stain negative for these proteases." (PMID 41974993, 2026).